OSMR (oncostatin M receptor)
Diseases named in the same sentence as OSMR in open-access papers (continued):
Sharing a sentence is not in itself a finding about the gene and the disease.
tumor (continued). "Our findings establish OSMR as a molecular linchpin connecting intrinsic tumor survival pathways (PI3K/CCNE2) with extrinsic immunosuppressive reprogramming (BMP5/TANs/CD8+T cells), providing a clinically actionable target to overcome treatment resistance in GC." (PMID 41653653, 2026). "Importantly, OSMR downregulation exhibited a more pronounced suppression of tumor growth in immunocompetent C57 mice compared to immunodeficient NSC mice, with a lower tumor volume ratio in the KO/NC group." (PMID 39815665, 2025). "Similarly, the tumor growth rate was slower in C57 mice treated with OSMR‐KO compared to the OSMR‐NC group." (PMID 39815665, 2025). "In addition, tumor cells also showed increased expression of OSMR, which suggests the presence of the OSM-OSMR axis in metastatic ccRCC potentially acting as an independent RANKL-inducing pathway." (PMID 38281962, 2024). "OSMR is widely expressed on various tumor cells, epithelial cells, and endothelial cells." (PMID 39422492, 2024). "OSMR showed relatively high expression in tumor cells compared to other cell types." (PMID 36973268, 2023). "IL-6 and OSMR play a role in tumor proliferation by activating transcription factors." (PMID 37671166, 2023). "In order to confirm the aberrant expression of OSMR in tumor tissue, we first performed RTqPCR." (PMID 35745569, 2022). "Importantly, our results reveal that OSMR activation in CAFs promotes the recruitment of OSM-producing myeloid cells to the tumor through OSM-induced secretion of chemokines, thereby inducing a feed-forward loop." (PMID 35192545, 2022). "OSM is a cytokine that interacts with OSMR as a ligand to induce tumor promotion or inhibition." (PMID 36551576, 2022). "Based on the results of target gene prediction, we found that its target gene OSMR was significantly highly expressed in MM, and it has been reported in the literature that OSMR can promote tumor cell proliferation, inhibit apoptosis, promote tumor metastasis, and promote tumor progression." (PMID 34422217, 2021). "Together, this emphasises the relationship between OSMR expression and the establishment of an immunosuppressive microenvironment in patients with PDA, and underscores a functional role of heterocellular OSM–OSMR signalling in mediating an immunosuppressive, tumour-promoting environment." (PMID 34921158, 2021). "Moreover, OSMR expression in stellate cells is required for co-culture dependent activation of phospho-STAT3 signalling in tumour cells." (PMID 34921158, 2021). "Depletion of OSMR had similar effects; namely, it significantly prolonged mouse survival (median survival: 13.5 vs. 21.5 or 22 days, both P = 0.0058), eliminated tumor necrosis, and diminished tumor growth, proliferation, and vessel density." (PMID 32248843, 2020). "Recently, a study demonstrated that OSMR is required for GBM tumor growth." (PMID 30859746, 2019). "In 3 of 5 tumor cases, OSMR was significantly down-regulated (left)." (PMID 19662090, 2009). "Importantly, based on our data for 7 Ba/Sq samples, we were able to identify higher enhancer activity associated with potential key genes in Basal tumour biology, including cell surface receptors (IL7R, OSMR, EGFR, MET) and transcriptional regulators (BNC2, HMGA2, KLF7, NR3C1)." (PMID 36944729, 2023). "Notably, Osmrhigh CAFs express higher levels of inflammatory signals such as Il6, Ccl7, Ccl2 and Cxcl1 in animal models of PDA, OSMR is expressed at increased levels in human PDA and is associated with a tumour-promoting immune infiltrate and worse patient outcome." (PMID 34921158, 2021). "Mechanistically, OSMR directly recruits PI3K, amplifying PI3K/AKT signaling to increase cyclin E2 (CCNE2) expression, thereby sustaining tumor cell survival under chemotherapy-induced stress." (PMID 41653653, 2026). "In the HPA database, only OSMR, IGFBP6, and IGHG2 were found, showing high levels of protein expression in tumor tissue of GBM patients for all three." (PMID 39815665, 2025).
tumor (continued). "In GBM, OSMR cooperates with its ligand OSM to activate STAT3 signaling, inducing a mesenchymal‐like phenotype that enhances tumor invasiveness and treatment resistance." (PMID 41498024, 2025). "This suggests that the protein expression of OSMR, IGFBP6, and IGHG2 was significantly elevated in the tumor tissue of GBM patients compared to normal control tissue." (PMID 39815665, 2025). "To investigate the role of the five genes (OSMR, G0S2, IGFBP6, IGHG2, and FMOD) in specific cells within the tumor tissue of GBM patients, we illustrated the distribution of these genes across different cell types." (PMID 39815665, 2025). "In summary, the mRNA expression of OSMR, G0S2, IGHG2, and FMOD was significantly upregulated in tumor tissue of GBM patients compared to normal control tissue." (PMID 39815665, 2025). "In our bioinformatics analysis, we observed that OSMR and FMOD were mainly distributed in astrocytes in GBM tumor tissue, while IGFBP6 was predominantly found in NPC cells, all of which are crucial factors in GBM pathogenesis." (PMID 39815665, 2025). "In line with this, its receptors OSMR and LIFR are expressed in PDGFRA+ oligodendrocytes and GBM tumor cells." (PMID 37692522, 2024). "TME-derived oncostatin M (OSM) was shown to mediate tumor progression and CSC expansion by activating its receptor, OSMR." (PMID 38236642, 2024). "These included well-known receptor tyrosine kinase genes (EGFR, TEK and OSMR) that activate MAPK and PI3K signaling pathways, and other tumor-promoter genes (ATP8B2, DAAM1, SLAMF8 and SRGN) as well as tumor-suppressor genes (A2M, DAPK1, RASSF8 and SOCS3)." (PMID 37190308, 2023). "Heterocellular Oncostatin M (OSM)—Oncostatin M Receptor (OSMR) signalling has also been shown to reprogram fibroblasts and regulate tumour growth and metastasis." (PMID 36358721, 2022). "While the protumoral effect of OSMR activation in cancer cells has been extensively described, little is known about the effects of OSM in the tumor stroma and our results shed light on the effects of OSM signaling in CAFs." (PMID 35192545, 2022). "Likewise, since bone marrow-resident cells express the gp130 subunit and many of the cytokine-specific receptors (e.g., LIFR and OSMR), the tumor cell production of these cytokines may also remodel the bone marrow microenvironment to make it more permissive for tumor colonization or dormancy." (PMID 32023849, 2020). "Further, we uncovered a significant relationship between ANXA2 and OSMR expression in clinical GBM specimens, and demonstrated their correlation with tumor histopathology and patient prognosis." (PMID 32248843, 2020). "After five weeks of development, the tumor volume was the same for both OSMR-KO mice and their WT littermates, suggesting a direct role of OSM on OSMR-expressing cancer cells to promote tumor development." (PMID 30559930, 2018). "Outside this grouping, a cartilaginous fish sequence falls within an OSMR (multifunctional) and LIFR (tumour metastasis suppressor) clade (BPP = 1.00; UB = 1.00%; PPP = 1.00)." (PMID 30442091, 2018). "Expression of OSMR correlates with the increased expression of the CSC marker CD44 and mesenchymal markers, most frequently at the invasive edge of the tumor near the OSM-secreting macrophages." (PMID 26742077, 2016). "OSMR is a receptor of Oncostatin M (OSM), an interleukin-6 (IL-6)-type cytokine identified as a potent suppressor of tumor cells." (PMID 19662090, 2009). "On the other hand, OSMR is not expressed by leukocytes but by non-hematopoietic malignant cells, as well as endothelial and mesenchymal cells forming the tumor environment." (PMID 41040517, 2025). "Notably, OSMR, IGFBP2, and LOXL1 are highly expressed in multiple signaling pathways involved in tumor‐related biological processes such as apoptosis, inflammatory responses, EMT, and adherens junctions." (PMID 41498024, 2025).
tumor (continued). "Moreover, CellChat analysis unveiled ligand-receptor pairs mediating communication between tumor epithelial cells and disulfidptosis-related TME subgroups, such as TNFSF12-TNFRSF12A, TNF-TNFRSF1A, OSM-(OSMR+IL6ST), OSM-(LIFR+IL6ST), HBEGF-EGFR, and EREG-EGFR." (PMID 38292868, 2024). "Our snRNA-seq data also showed that macrophages express OSMR’s major ligand oncostatin M (OSM), suggesting that ccRCC tumor cells may interact with macrophages through OSM signaling transduction." (PMID 36973268, 2023). "Indeed, in the TSPO HIGH III cluster we observed a significant overexpression of the MES-like TAM tumor interaction genes OSM, OSMR, STAT3 and of CD44." (PMID 37697350, 2023). "In addition, malignant cells also had frequent interactions with myeloid (FMNL1+) cells via many ligand-receptor pairs, such as OSMR-OSM, which took participate in the process and invasion of tumor cells 44-47." (PMID 37859818, 2023). "The expression of OSMR and LRP6 in tumor cells and SERPINF1 in stromal cells was detected by IHC." (PMID 37333017, 2023). "However, in infiltrating carcinomas; high expression of OSMRβ (77.5%) and gp130 (74.1%) proteins have been seen, with OSM localized in 100% of tumor samples studied." (PMID 37841259, 2023). "We also confirmed that the protein levels of OSMR are considerably increased in tumor tissues, compared to normal tissues, when using immunohistochemistry (IHC) data from the Human Protein Atlas (HPA)." (PMID 36551576, 2022). "It is well known that most tumors have a heterogenous microenvironment, and therefore, even a tumor with high OSMR expression is likely to have a few malignant cells which do not have OSMR expression." (PMID 35745569, 2022). "We ascribed causality to the stromal function of the OSM axis by demonstrating reduced tumor burden of syngeneic tumors implanted in mice lacking OSMR." (PMID 35192545, 2022). "However, while the tumor samples had varying degrees of OSMR expression, the normal muscle tissue showed no expression indicating that OSMR is a viable target for therapy regardless of metastatic status." (PMID 35745569, 2022). "Consistent with this, knockdown of OSMR in the HGG stem cell lines reduced their tumorigenicity in an intracranial model, and knockdown of Osmr in EGFRvIII-expressing mouse astrocytes robustly reduced their in vivo tumor growth by attenuating cell proliferation." (PMID 27551537, 2016). "Furthermore, the metastatic SS mouse model expressed OSMR at a 22.4-fold increase over the non-metastatic model, suggesting that an OSMR targeted treatment might be more effective against aggressive tumor phenotypes." (PMID 35745569, 2022). "One gene that is likely to drive selection of 5p gain is the oncostatin-M receptor (OSMR; located at 5p13.1), which is commonly up-regulated in cervical SCC and produces a significantly worse clinical outcome when over-expressed, independent of tumour stage 4." (PMID 23765377, 2013). "Our data demonstrate that the OSM receptor (OSMR), but not IL-6 or its receptor, is expressed by all human and canine OSA cell lines and canine OSA tumor samples; additionally, OSM expression was noted in all tumor samples." (PMID 21481226, 2011).
cancer (41 papers, 2008 to 2025). A tumor composed of atypical neoplastic, often pleomorphic cells that invade other tissues. "First, in addition to the increased presence of OSM in the tumor microenvironment, cancer cells can also express high levels of OSM receptor (OSMR), which is associated with adverse clinical outcomes." (PMID 24675570, 2014). "We also observed a significant reduction in EMT-associated genes and cancer stemness-associated genes and increase in E-Cadherin and epithelial cell marker CD24 when OSMR is knocked down in both OVCAR8-CisR and A2780-CisR resistant cells." (PMID 38839865, 2024). "Recent studies including ours have reported that Oncostatin M receptor (OSMR) is highly upregulated in aggressive cancers and is associated with unfavorable outcome in cancer patients." (PMID 38839865, 2024). "Taken together, our results suggests that anti-OSMR antibody in combination with cisplatin therapy are effective in inhibiting cancer stemness and sensitizing cisplatin." (PMID 38839865, 2024). "Raven Biotechnologies has developed an anti-OSMRβ antibody (US7572896B2) designed for diagnosis of human cancers with high OSMRβ expression, as well as treatment for a variety of human cancers." (PMID 37841259, 2023). "Oncostatin M (OSM)/oncostatin M receptor (OSMR) signaling regulates the interactions among CAFs, cancer cells and immune cells, thereby reprogramming the pro-tumorigenic and pro-metastatic TME." (PMID 38235137, 2023). "While the ligand OSM was only expressed by the myeloid cell populations, we found that the receptor OSMR was mainly expressed by fibroblasts, cancer cells, and endothelial cells." (PMID 35192545, 2022). "Altogether, our data reveal that OSM and OSMR are stroma-expressed molecules, and point to paracrine OSM/OSMR signaling in cancer, as ligand and receptor are expressed by different cell types in the TME." (PMID 35192545, 2022). "OSM, a member of the IL-6 family of cytokines, binds to OSMR and then can either promote or inhibit the growth of various cancer cells." (PMID 35036597, 2022). "OSMR was consistently expressed mainly in epithelial/cancer cell populations, whereas the ligand OSM was specifically expressed in macrophages." (PMID 36551576, 2022). "Together, our data demonstrate that OSM/OSMR signaling activates CAFs and that this contributes to cancer progression." (PMID 35192545, 2022). "Inhibition of OSM and/or OSMR has demonstrated antitumor effects and has recently been receiving increased attention as a possible cancer therapy." (PMID 29898744, 2018). "There remains a requirement for further studies using clinical material to confirm the relationship between OSMR overexpression and neoplastic progression in new, independent sets of tissue from cervical SCCs, as well as carcinomas from other sites." (PMID 24659184, 2014). "As a result, we found that 3′-phosphoadenosine 5′-phosphosulfate synthase 2 (PAPSS2), γ-tubulin gene 2 (TUBG2), NTRK2, B4GALT1, and OSMR as well as SFRP4 harbored cancer-specific methylation with high frequencies (>30%)." (PMID 19662090, 2009). "Additionally, two pharmaceutical companies have patents targeting OSMRβ in both cancer and heart disease." (PMID 37841259, 2023). "Thus, promoter methylation is a key regulator of OSMR expression and all of these results support a suppressive function for OSMR in human cancer." (PMID 19662090, 2009). "Studies on B4GALT1 and OSMR have been reported in human cancer." (PMID 19662090, 2009). "However, the association of OSMR-signaling with integrins and the crosstalk between OSMR and integrin signaling were not well established before in cancer and particularly in the context of cisplatin resistance." (PMID 38839865, 2024). "Thus, decreased numbers of Ly6G+ and F4/80+ myeloid cells may explain, at least in part, the strong antitumoral and antimetastatic effect of OSMR depletion in the MMTV-PyMT cancer model." (PMID 35192545, 2022).
cancer (continued). "The remaining nine surface proteins identified solely (ANTXR1, AG1, DCBLD2, EFNB1, EMB, OSMR, SLC1A5) or found upregulated (ATP1B3 and ITGB1) on the MCF10A surface had no direct association with embryonic development signaling in the context of KRas mutant signaling in cancer cell lines." (PMID 27894102, 2016). "Mechanistically, exosomal circPLEKHM1 promoted PABPC1-eIF4G interaction to facilitate the translation of the oncostatin M receptor (OSMR), thereby promoting macrophage polarization for cancer metastasis." (PMID 38509870, 2024). "The heatmap showed that the 15 CpG sites (located on B3GALNT1, C6orf97, FAM72A, FAM72B, LIFR, OSMR, ZNF264, and ZNF543) well‐distinguished CRC from adjacent normal tissues, WBCs, and 28 other types of cancer in TCGA, as well as 23 other types of cancer in GEO." (PMID 37649326, 2023). "The expression level of OSMR correlates with the reactivity of OSM, and STAT3 activation induced by the OSM–OSMR interaction is observed in various cells, including cancer and immune cells." (PMID 36551576, 2022). "To assess the correlation between OSM signaling and LOXL2 expression in cancer patients, we analyzed the expression of LOXL2 mRNA in patients and compared it to OSMR mRNA expression." (PMID 34011405, 2021). "To assess the correlation between OSMR and LOXL2, we used RNA-Seq data from The Cancer Genome Atlas (TCGA) to assay transcriptional expression of biopsied patient samples in several cancer subtypes." (PMID 34011405, 2021). "Another intriguing potential target candidate in this list is from non-oncology space, OSMR-receptor for Oncostatin M (OSMR), which exhibited overexpression across 10 cancer indications in our analysis." (PMID 39186767, 2024). "Because the antibody is specific for OSMR, which has been found to be overexpressed in multiple cancer types, this therapy is capable of treating multiple types of cancer regardless of their classification." (PMID 35745569, 2022). "Additionally, we investigated whether the expression of OSMR and LIFR-AS1, which are the genes whose methylation patterns are specific in differentiating CRC from other mentioned cancers, differs between primary CRC, CRC NATs and CRLM." (PMID 39766812, 2024). "However, no mutations were identified in the cancer hotspot locations of IL23R, IL12Rß1, IL12Rß2, OSMR, TYK2, and JAK2 across all mutant distributions." (PMID 36232773, 2022). "Therefore, the STAT/gp130/OSMR/JAK feedforward loop and NF-κB (REL, NFKB1) may operate combinatorially in cancer." (PMID 32102440, 2020). "The elevated OSMR expression coincides with acquisition of the CSC cell surface marker CD44, and parallels the elevated expression of epidermal growth factor receptor and Transforming Growth Factor-β receptor type I, two receptor kinases with established roles in cancer development and progression." (PMID 24675570, 2014).
metabolic disorders (5 papers, 2017 to 2022). "This review summarizes the roles of the oncostatin M receptor (OSMRβ) as a modulator of adipocyte development and function its contributions to immunological adaptations in AT in metabolic disease states." (PMID 33854494, 2020).
cardiovascular diseases (4 papers, 2017 to 2023). "Given the imbalance in research studies between interleukin-6 and the other members of the IL-6 cytokine family, it is time to reconsider the involvement of the OSMR/gp130 as well as the LIFR/gp130 complexes in human cardiovascular diseases." (PMID 35163735, 2022). "Oncostatin M (OSM) is a secreted cytokine mainly involved in chronic inflammatory and cardiovascular diseases through binding to OSM receptor β (OSMR-β)." (PMID 28258089, 2017). "We investigated the impact of common genetic variants in OSM and its receptors, OSMR and LIFR, on overall plaque vulnerability, plaque phenotype, intraplaque OSMR and LIFR expression, coronary artery calcification burden and cardiovascular disease susceptibility." (PMID 33959646, 2021).
heart disease (3 papers, 2022 to 2025). "In mouse models of heart disease, OSM elicits opposing effects via activation of the type II receptor complex (OSMR/gp130)." (PMID 35163735, 2022).
infection (2 papers, 2016 to 2025). The state of being infected such as from the introduction of a foreign agent such as serum, vaccine, antigenic substance or organism. "The upregulation of IL13RA1, OSMR, CRLF2, and IL6R in our study may indicate responses to maintain neuromuscular integrity under infection-induced stress." (PMID 40943072, 2025). "We next analyzed whether EcoHIV infection regulates expression of OSM receptor subunits (gp130 and OSMR-β) in cultured primary microglia." (PMID 27287400, 2016). "Since OSM may play an important role in HIV-1-associated neuropathogenesis, we further investigated whether infection with a chimeric HIV-1 (EcoHIV/NL4-3-GFP virus (EcoHIV)) induces the expression of OSM and/or its receptors (OSMR-β and gp130) in cultured microglia and astrocytes." (PMID 27287400, 2016).